IFNG (interferon gamma)
Diseases named in the same sentence as IFNG in open-access papers (continued):
Sharing a sentence is not in itself a finding about the gene and the disease.
tumor (continued). "Importantly, many studies showing correlation between exercise and increasing immune cell tumour infiltration in murine models have been undertaken in hot tumours with TMEs rich in tumour inhibiting T cells and cytokines such as interferon gamma (IFN-γ) and therefore, inherently immunogenic." (PMID 38149260, 2023). "Furthermore, eNVs-FAP–activated immune responses could initiate tumor ferroptosis by releasing interferon-gamma (IFN-γ) from CTLs and depleting FAP+ CAFs." (PMID 36922504, 2023). "Furthermore, the increased expression of IFNA.down and IFNG.down signatures observed in our study in dnMBC may point to decreased interferon signaling, which may have a direct impact on the local anti-tumor immune response." (PMID 37686617, 2023). "Our model implies that the reduced activity of CTLs and in particular the apparent reduction in IFNG, which preceded the disappearance of CTLs in the tumor by several days, could be explained by the development of an exhausted phenotype in the tumor-infiltrating CTLs." (PMID 37182110, 2023). "We demonstrated that YB1 may exhibit anti-tumor effect mainly based on IFNγ induction." (PMID 38020179, 2023). "In addition to their killing of tumor cells, CTLs inside the tumor produce IFNG." (PMID 37182110, 2023). "We next tested whether tumor [89Zr]Zr-anti-IFNγ uptake would correlate with ICI outcomes." (PMID 38130991, 2023). "Finally, the GLUT1+ area, that reflects hypoxia in tumour tissues 37, was diminished by anti-IFNγ treatment, implying that anti-IFNγ might alleviated hypoxia in the tumour." (PMID 37056922, 2023). "Although previously recognized as a costimulatory molecule that promotes T cell activation and interferon-gamma (IFN-γ) production, the majority of currently available data confirm that B7-H3 exerts coinhibitory effects on T cell responses, which may allow tumor cells to evade immune destruction." (PMID 37110590, 2023). "Additionally, pretreatment of B16-OVA cells with AC484 led to significantly more tumour killing and cytokine production (IFNγ and TNF) by untreated SIINFEKL-specific OT-I T cells in vitro than vehicle-treated cells, a result consistent with enhanced antigen presentation." (PMID 37794185, 2023). "Therefore, cisplatin largely destroys tumour blood vessels by stimulating IFNγ production." (PMID 37056922, 2023). "Interestingly, when we treated tumor cells with IFNγ, GSDMB was also increased in tumor cells." (PMID 37587833, 2023). "In fact, previous observations suggested that IFNg and TNF may suppress tumor growth in different conditions, although the ultimate effect of these cytokines on tumor progression in vivo is context-dependent as IFNg may, in fact, improve the metastasis of some tumors." (PMID 37515143, 2023). "Additionally, by loading probes into the CREKA-lipo nanoparticles, the nanomaterial might be used to diagnose the degree of vascular damages in tumour chemotherapy and inform the chances for application of IFNγ neutralizing antibody." (PMID 37056922, 2023). "Thus, we hypothesize that the anti-tumor role of cytotoxic Tr1 cells in this context is driven by the ability of PD1 blockade to preferentially enhance production of Th1 cytokines such as IFNγ over IL10 in Tr1-like CD4 T cells from human cancer samples." (PMID 37654482, 2023). "At the sites of initial tissue damage, infection or tumor formation, the attraction of pro-inflammatory T helper cells Th1 and Th17 and Natural Killer (NK) cells establishes the earliest defense against these insults by secreting IFNγ, IL-1β, TNF and related cytokines." (PMID 37296860, 2023). "However, its expression can be upregulated by several factors including interferon gamma (IFN-γ) and may vary over time and across multiple tumor sites." (PMID 37251920, 2023). "Thus, we speculate that the increased levels of IFNγ in the tumor microenvironment may have led to the upregulation of PD-L1 in association with the loss of Her-2/neu expression in the patient’s tumor." (PMID 38203458, 2023).
tumor (continued). "Interestingly, we also observed the expression of effector markers, such as IFNG in SC-2 cells, indicating that SC-2 cells might function as cytotoxic T cells to directly kill tumor cells, as reported in a previous study." (PMID 36049666, 2023). "Suppressing the proliferation potential as well as IFNγ production capacity of effector T cells, these Treg cells might be inhibiting antitumor immunity, thereby hindering immune-elimination of CSCs during tumor initiation." (PMID 38038865, 2023). "Indeed, mice carrying Treg-specific Ezh2 deficiency showed a reduced growth of different types of tumors (e.g., CRC, melanoma, prostate cancer) in association with the reprograming of tumor-infiltrating Tregs in anti-tumor effector cells (e.g., IL-2, IFNγ, and TNF)." (PMID 36900330, 2023). "Moreover, in the tumor microenvironment, PD-L1 expression might be induced by interferon-gamma secretion via effector T cells." (PMID 36836455, 2023). "To test this hypothesis, we inhibited IFNγ signaling using an anti-IFNγR1 blocking antibody or enhanced IFNγ secretion with a human recombinant interleukin-12 (huIL12) in our extended in vitro co-culture tumor cell killing assay." (PMID 37550294, 2023). "In a particularly elegant study, it was demonstrated that IFNγ pathway-mutant tumors are more sensitive to CD8+ T cell-mediated eradication due to the loss of protection by IFNγ-induced PD-L1, but become more resistant when intermixed with PD-L1-producing wildtype tumor cells." (PMID 37398651, 2023). "In addition, the accumulation of IFNγ-producing CD8+ T cells in the TME could be the result of overtly activated clones specific for tumor antigens that contribute to feeding IFNγ to the inflammatory milieu but no longer eliminate tumor cells." (PMID 36980678, 2023). "Therefore, compared with systematically injection of IFNγ, targeted-IFNγ supplement may be more effective for tumor treatment." (PMID 38020179, 2023). "Surprisingly, when co-cultured with tumor cells, the level of cytokine released by δ-TCRγδ-T and γ-TCRγδ-T cells, such as IFNγ and GM-CSF, was lower than those by CAR-T cells, except that in SK-MEL-5 cells, which could account for the ineffective killing of SK-MEL-5 by CAR-T cells." (PMID 37349298, 2023). "Moreover, IFNγ has the ability to boost tumor antigen presentation by increasing MHC I expression." (PMID 36875059, 2023). "Besides, tumor-infiltrating CD8+ T-cells in males produced less IFNγ and TNF than in females." (PMID 37715192, 2023). "Moreover, deficiency of TNFR2 also markedly impaired in vivo growth of MC38 or CT26 in the syngeneic C57BL/6 mice or BALB/c mice, respectively, accompanied by the decrease in soluble TNFR2 levels in the circulation and the increase in the number of tumor-infiltrating IFNγ+ CD8 cells." (PMID 36923938, 2023). "Moreover, γ-H2AX+ area in the tumour tissue was increased by neutralising IFNγ treatment." (PMID 37056922, 2023). "Mice with NK cell activating factors, including IFNγ, perforin 1 (PRF1), or TRAIL deficiency by gene knockout or antibody-caused neutralization, were more susceptible to metastatic incidences following challenges with tumor cell inoculation or with carcinogen-induced tumors." (PMID 37190251, 2023). "However, it is questionable whether IFNγ can be used as a monotherapy to treat tumor metastasis, considering that systemic infusion of IFNγ could not inhibit the tumor metastasis to the lung." (PMID 38020179, 2023). "Indeed, compared to the WT, EGFR mutant cancer cells downregulate the expression of CXCL10, chemoattractant for CD8 T cells, and CCL21, important for the accumulation of NK cells and naïve T cells, and whole tumor extracts revealed a trend toward a lower expression levels of IFNγ." (PMID 37180110, 2023). "Besides IFNγ, other cytokines contribute to the anti-PD-1-driven anti-tumor response." (PMID 37189417, 2023).
tumor (continued). "When exposed to the tumor microenvironment for a long time, the balance is broken and the inhibition signal is enhanced, leading to T cell depletion, and loss of proliferation, secretion of cytokines (including IL-2, TNF, and IFNγ), and degranulation by T cells." (PMID 35770416, 2023). "For example, CDK4/6 inhibition was shown to enhance antigen presentation, which accompanied an increased IFNγ response; interestingly, the authors linked this outcome with downregulation of DNMT1, hypomethylation of TEs, and enhanced chemokine secretion that stimulated tumor immune surveillance." (PMID 37055433, 2023). "Although the importance of IFNγ signaling in immunotherapy has become undisputed in recent years, both experimental and preclinical studies have been largely focusing on perturbations in this pathway that contribute to tumor immunogenicity editing and immune escape." (PMID 35395848, 2022). "As immunosuppressive molecules (e.g., PD‐L1, IDO1, and IL‐18BP) that can be induced by interferon‐gamma (IFN‐γ) are generally important to facilitate immune evasion by tumor cells, we wondered whether the expression of these immunosuppressive molecules in NPC cells is affected by CBX1." (PMID 36310139, 2022). "Therefore, IFNG-induced ferroptosis is a double-edged sword for tumor development." (PMID 35692844, 2022). "Therefore, how oleic acids in the context of IFNγ treatment can promote tumor cell ferroptosis remains unclear and will be an interesting topic for future studies." (PMID 35459217, 2022). "In addition, E7-specific CD8+T cells secreted more IFNγ when co-cultured with irradiated tumor cells, suggesting that they may have enhanced recognition of irradiated versus non-irradiated TC-1 tumor cells." (PMID 34971406, 2022). "Furthermore, interrogation of the HIS in immune organs and tumors by flow cytometry revealed increased Granzyme B+, TNFα+ and IFNγ+ CD4+ T cells among the human tumor infiltrating leukocytes (TIL) that correlated with reduced tumor growth in the combination-treated HIS-mice." (PMID 36419897, 2022). "Interestingly,ELISpot analysis revealed that the major MHC-I restricted epitope arising fromthe envelope glycoprotein (env) of Emv2, theendogenous ecotropic murine leukaemia retrovirus (eMLV) in C57BL/6J mice,induced IFNγ secretion from splenocytes harvested from KPAR1.3 tumour-bearingmice." (PMID 35930804, 2022). "The tumor infiltrating lymphocytes may behave differently in cancers and myositis, either taking part in the muscle inflammatory infiltrate, or increasing the expression of checkpoint inhibitors in cancer by means of IFNγ." (PMID 35806366, 2022). "We also found that ANK1 (P = 0.0018), IL4I1 (P = 1.2e−12), IDO1 (P = 0), IFNG (P = 0)and MAPK12 (P = 2.2e−12) are positively correlated with PD-L1 expression in CRC cancer which has been reported to be associated with worse prognosis and counteract effect of tumor-infiltrating lymphocytes." (PMID 35962343, 2022). "Moreover, we recently demonstrated that Met-induced mitochondrial ROS (mtROS) stimulated both Glut-1expression on cell surface of tumor-infiltrating CD8+ T cells (CD8TILs) to produce IFNγ and activation of Nrf2/mTORC1/p62 axis for CD8TILs to proliferate in tumor." (PMID 35844589, 2022). "In a murine model, reductions in lactic acid production (LHDAlow) resulted in slower tumor growth with the increased infiltration of IFNγ-producing T cells in the tumors, suggesting that LDHA may be an important therapeutic target for improving immunotherapies." (PMID 35203357, 2022). "Thus, we hypothesized that inactivation of STUB1 may reverse ICB resistance by increasing tumour cells’ sensitivity for IFNγ." (PMID 35982220, 2022). "If successful in clinical trials, the effect of blocking anti-CD100 antibodies on inhibition of pro-tumor IL-17-producing γδ T cells versus antitumor IFNγ-producing γδ T cells will be of interest and may help inform which solid tumor indications are most suitable for treatment." (PMID 35480230, 2022).
tumor (continued). "In addition to antitumor effects, IFNγ can contribute to tumor immune evasion." (PMID 34385592, 2022). "Hence, anti-tumor responses and signals may also upregulate inhibitory genes and signaling pathways such as IFNγ, CTLA-4, and PD-L1 in immune cells." (PMID 36142818, 2022). "Furthermore, IFNγ also presented an increase in tumor tissue that was more pronounced in stage II." (PMID 36139645, 2022). "The production of IFNg may act as a major inductor of NK cell cytotoxicity toward tumor cells." (PMID 35692772, 2022). "Prolonged treatment with IFNγ could inhibit the growth of tumour cells." (PMID 35982220, 2022). "The poor outcome of the subclonal ANK1 mutation may be caused by upregulation of IL4I1, IDO1, IFNG and MAPK12 which showed potential roles in tumor immune evasion through accumulation of immunosuppressive cells such as regulatory T cells and myeloid derived suppressor cells." (PMID 35962343, 2022). "It was found that IFNγ could cooperate with AA to induce tumor cell ferroptosis." (PMID 36313765, 2022). "Furthermore, 24-h re-stimulation of the EpiTCer activated CD8+ T cells with ANRU tumor cells resulting in a more efficient tumor recognition than the 6-h re-stimulation, at all tested bead/DC ratios, as measured by degranulation (CD107a) and IFNγ production." (PMID 35433456, 2022). "Resistance mechanism to anti-PD-1 has been recently proposed to be associated with tumor-associated macrophages that could bypass the targeting of T cells or with mutation in key signaling pathways such as JAK1/2 kinases inducing IFNγ lack of response." (PMID 35339889, 2022). "First is an “extrinsic” mechanism where an anti-tumor cellular immune response is driven by micro-environment cells, such as natural killer cells (NK) and CD8+ tumor-infiltrating lymphocytes (TILs), producing IFNγ; this, in turn, may induce PD-L1 expression on tumor cells." (PMID 35628647, 2022). "To test whether the tumor-specific CD4 T cells were the source of the crucial IFNγ, we treated tumor-bearing mice with IFNγ deficient Marilyn CD4 T cells and found that, similarly to the IFNγ blocking experiment, most of the antitumor effect was lost." (PMID 35903540, 2022). "Hence, while SMAD4 signaling may modestly reduce PD-L1 expression in tumor cells, SMAD4 functions as an indirect inducer of PD-L1 by enhancing the recruitment of tumor-infiltrating IFNγ-producing T-lymphocytes." (PMID 35155243, 2022). "For instance, avelumab, a fully human IgG1 anti–PD-L1 mAb, was shown to increase the secretion of interferon γ (IFNγ) from anti-tumor immune effector cells, which could enhance both PD-L1 expression and antibody-dependent cellular cytotoxicity (ADCC)-mediated lysis." (PMID 36009390, 2022). "Thus, IFNγ may have both immunostimulatory, anti-tumor effects or immunosuppressive, pro-tumor effects, depending on the context in which it is produced." (PMID 36551577, 2022). "To answer these questions, and further investigate the mechanism of CD4-mediated tumor rejection, we used different bone marrow donor mice to obtain sets of chimera mice that allowed us to separate, at the cellular level, antigen presentation from IFNγ signaling occurrences." (PMID 35903540, 2022). "Meanwhile, NK-S100A8 from high tumor infiltration group displayed enhanced “hydrogen peroxide metabolic process”, “hydrogen peroxide catabolic process” and “reactive oxygen species metabolic process” as well as impaired “response to interferon-gamma” and “regulation of superoxide anion generation”." (PMID 36532059, 2022). "The levels of IL-2 and IFNγ cytokines released from unstimulated lymphocytes treated with tribodies were found to be very low, thus proving that the effects of the tribodies are exerted only on activated lymphocytes expressing the ICs in the presence of tumor cells." (PMID 36071464, 2022).
tumor (continued). "Subclonal ANK1 mutation is related to adverse outcomes of CRC through increasing IL4I1, IDO1, IFNG and MAPK12, which may cause tumor immune escape through the accumulation of immunosuppressive cells such as regulatory T cells and myeloid derived suppressive cells." (PMID 35962343, 2022). "Interestingly, patient 17, who had the exacerbated humoral response, had zero IFNg spots both at baseline and at follow-up visits, suggesting that in his predominating humoral response, the activation of specific anti-tumor CD8+ T cells were inhibited or diminished." (PMID 35740441, 2022). "Fourth, SBRT has been shown to enhance the magnitude of the immune response by producing more neoantigens, which could recruit a large number of T cells and promoted the release of inflammatory mediators related to tumor apoptosis, such as IFNγ, TNF-α, TGβ−1 and interleukins." (PMID 36084485, 2022). "Furthermore, immunotherapy sensitizes tumors to radiotherapy by promoting tumor-cell ferroptosis through IFNγ-induced SLC7A11 suppression, suggesting that ferroptosis may serve as a determinant of synergy between radiotherapy and immunotherapy." (PMID 35847022, 2022). "Moreover, IFNγ has been demonstrated to induce a strong anti-angiogenic effect on tumor models." (PMID 36330506, 2022). "By measuring the variance of activated genes such as IFNα, IFNγ, TNFα and TGFβ present in the tumor tissue and in normal mammary tissue, they defined a metric denoted “phenotypic volume”, which was used to characterize the phenotypic expansion of immune cells in the tumor microenvironment." (PMID 35804950, 2022). "Thus, in the ‘preventative setting’, CD4+ T cells through IFNγ seem to be responsible for vessel fortification through pericyte recruitment consistent with previous studies of angiogenesis in early tumor development." (PMID 35712656, 2022). "The appropriate dose of IFNγ in a tumor setting is currently unknown." (PMID 35806366, 2022). "Furthermore, in a xenograft mouse model, 60 mg/kg of QUE inhibited tumor growth, the population of cytotoxic T cells increased and the expression of cytokines such as interferon-gamma (IFN-γ) and granzyme B in the tumor microenvironment increased to kill the tumor." (PMID 36551742, 2022). "In mouse tumor models, B-MFs promote shrinkage of the tumor-infiltrating IFNγ+ CD4 T cell pool and increase cancer progression and metastasis, suggesting that this cancer-induced transdifferentiation pathway is functionally relevant and hence could serve as an immunotherapeutic target." (PMID 36104343, 2022). "Interestingly, we found that PD-L1 expression in tumor tissue sections could only be detected in cells surrounded by NK cells, further suggesting that the expression of PD-L1 is dependent on the tumor microenvironment and IFNγ secreted by NK cells." (PMID 36525420, 2022). "Thus, CWs could reverse an immunosuppressive tumor microenvironment by increasing IFNγ production and inhibiting PD-L1 expression, which then probably activated autologous CIK that synergized (Z)-BP and acted on the GBM." (PMID 35646111, 2022). "To validate expression of IL-12 and test whether tracer administration impacts downstream IL-12/IL-12R signaling, we performed qRT-PCR on flash frozen tumor tissue to measure expression of IL-12β and key proinflammatory cytokines indicative of active IL-12 signaling: IFNγ, TNFα, and IL-18." (PMID 35634303, 2022). "CD8TILs metabolism may be unique to Met’s treatment because Met upregulates Glut-1 level on the surface of the CD8TILs; moreover, it elevates the glucose concentration in a tumor, likely through the downregulation of the glycolysis of tumor cells in an IFNγ-dependent manner." (PMID 35844589, 2022).